DMP1-AS1 (DMP1 and DSPP antisense RNA 1)
Synonyms: AC093895.1; lnc-SPARCL1-1
Gene: Long non-coding RNA gene on chromosome 4 (87,568,035 to 87,741,390, reverse strand). Ensembl gene ENSG00000249001.
Diseases named in the same sentence as DMP1-AS1 in open-access papers:
DMP1-AS1 is named in the same sentence as 1 disease in open-access papers, as found by Europe PMC text mining. Sharing a sentence is not in itself a finding about the gene and the disease.
DMP1-AS1 shares sentences with these, for which no sentence is quoted: tumor (1 paper).